HAMP (hepcidin antimicrobial peptide)
Diseases named in the same sentence as HAMP in open-access papers (continued):
Sharing a sentence is not in itself a finding about the gene and the disease.
Cognitive impairment (1 paper, 2018). Abnormal cognition is characterized by deficits in thinking, reasoning, or remembering. "However, data about the impact of HAMP gene variants in neurodegenerative disease and cognitive impairments are still lacking." (PMID 29518107, 2018). "To gain insights on iron-dependent processes in cognitive impairment, we extended the analyses to further SNPs: FPN1 -8CG, HAMP -582AG and TF P570S." (PMID 29518107, 2018).
COVID-19 (1 paper, 2022). A disease caused by infection with severe acute respiratory syndrome coronavirus 2. "We found a strong increase in HAMP mRNA levels in blood samples of COVID-19 patients compared to healthy donors and convalescent patients." (PMID 35181867, 2022). "Furthermore, we found the same enhancement of HAMP mRNA levels in the blood of severe COVID-19 patients." (PMID 35181867, 2022).
diabetic neuropathy (1 paper, 2023). A chronic, pathological complication associated with diabetes mellitus, where nerve damages are incurred due to diabetic microvascular injury involving small blood vessels that supply these nerves, resulting in peripheral and/or autonomic nerve dysfunction. "Similarly, GeneCards also reports an association of kidney function with other top predicted Diabetic Neuropathy genes having no PubMed support, including HAMP (predicted gene #2) and CHDH (predicted gene #8)." (PMID 36791052, 2023).
dilated cardiomyopathy (1 paper, 2016). Cardiomyopathy which is characterized by dilation and contractile dysfunction of the left and right ventricles. "In addition, decreased cardiac HAMP expression has been reported in a transgenic mouse model of dilated cardiomyopathy, where the phenotype was ameliorated following transgenic overexpression of cardiac hepcidin." (PMID 27897970, 2016).
glioma (1 paper, 2021). A benign or malignant brain and spinal cord tumor that arises from glial cells (astrocytes, oligodendrocytes, ependymal cells). "TRIM38, CCR5, PLAU, P2RY8, and PROS1 were upregulated in glioma tissues, while HAMP and S100A9 were downregulated." (PMID 34954691, 2021). "We observed that the IRSs of PROS1, P2RY8, PLAU, CHI3L2, MSR1, CCR5, and TRIM38 were higher than its corresponding IRSs in low-grade glioma, while the IRSs of HAMP, CARD16, and S100A8 in high-grade glioma were lower than low-grade glioma." (PMID 34954691, 2021). "The results showed that TRIM38, CCR5, PLAU, P2RY8, and PROS1 have a higher immunoreaction score (IRS) in tumors than normal tissues (p < 0.05), while the IRS of HAMP and S100A9 in gliomas were lower than normal tissues (p < 0.05)." (PMID 34954691, 2021).
hepatitis B (1 paper, 2022). "This study suggests that HAMP as a kinase may have the function to activate immune cells and prevent the transformation from hepatitis B to HCC." (PMID 36105485, 2022). "The results showed that the HAMP gene expression level in HCC was positively correlated with multiple immune cells (p < 0.01), whereas it was negatively correlated with multiple immune cells in hepatitis B (p < 0.01)." (PMID 36105485, 2022).
iron metabolism disorders (1 paper, 2015). "Abnormal levels of HAMP expression alter plasma iron parameters and lead to iron metabolism disorders." (PMID 25943891, 2015).
kidney damage (1 paper, 2024). "Promising biomarker candidates for kidney damage in Bothrops snakebites were retinol-binding protein (RBP4), beta-2-microglobulin (B2M), cystatin-C (CST3), hepcidin (HAMP), and fatty acid-binding protein (L-FABP)." (PMID 38536893, 2024).
morbid obesity (1 paper, 2018). An excess of body weight, normally defined as an individual with a body mass index greater than 35 or a body weight greater than one hundred percent of ideal body weight. "In our patient cohort without morbid obesity, hepatic HAMP mRNA levels showed a good correlation to the serum hepcidin values measured by ELISA." (PMID 29871592, 2018).
ovarian carcinoma (1 paper, 2023). A malignant neoplasm originating from the surface ovarian epithelium. "The expression of HFE, MTF1, and BMP6 involved in iron regulation was associated with improved PFS in ovarian cancer, whereas the expression of HIF1A, GPI, and HAMP involved in this process was associated with poor PFS in ovarian cancer." (PMID 38186569, 2023).
peritonitis (1 paper, 2014). Inflammation of the peritoneum (tissue that lines the abdominal wall and covers most of the organs in the abdomen). "Expression of HAMP mRNA was 60-times higher in PD cells from peritonitis patients relative to uninfected patients." (PMID 25549329, 2014). "Expression of both CAMP (18.3-fold±9.4, p<0.01), and HAMP (64.1-fold±7.0, p<0.001) was increased in peritonitis PD cells from compared to non-infected patients." (PMID 25549329, 2014).
polycythemia (1 paper, 2015). Abnormally high mass or concentration of red blood cells in the blood, either due to an increase in erythropoiesis or a decrease in plasma volume. "Consistently, studies in mice with genetic alterations in iron regulatory genes, including inactivating mutations in the gene encoding hepcidin (HAMP), have shown a transient polycythemia." (PMID 26779261, 2015).
sickle cell anaemia (1 paper, 2024). "This study explored the potential link between genetic variants of HAMP rs10421768 and the disease severity in individuals with sickle cell anaemia." (PMID 38935685, 2024). "The sporadic nature of blood transfusion therapy coupled with the alteration of HAMP genes may exacerbate the risk of iron burden in sickle cell anaemia (SCA) patients." (PMID 38935685, 2024).
Venous thrombosis (1 paper, 2022). Formation of a blood clot (thrombus) inside a vein, causing the obstruction of blood flow. "The second gene is HAMP, coding for hepicidin whose increased plasma levels have recently been reported to associate with the risk of venous thrombosis." (PMID 35387445, 2022).
tumor (23 papers, 2013 to 2025). "HAMP, a regulator of iron metabolism, is frequently upregulated in GC and associated with inflammation and tumor progression." (PMID 41244835, 2025). "In patients with stage 3 GC, poor OS and FP were associated with increased HAMP expression, depending on the stage of the tumor." (PMID 41244835, 2025). "We performed sequence analyzes of HAMP gene in all tumor and normal specimens and identified mutations in the heterozygous state in 4 patients." (PMID 24078156, 2013). "Elevated TFR1 and reduced HAMP mRNA levels were observed in tumor tissues in comparison to NTL, respectively." (PMID 39820815, 2025). "Volcano plots were utilized to visualize the expression patterns of these genes, revealing that genes such as GPC3 and SPINK1 were significantly upregulated in the tumor group, while genes including HAMP and CYP1A2 were markedly downregulated." (PMID 40864066, 2025). "Using XIANTAO online tools, the results show that HAMP levels were higher in tumor samples (P < 0.001), which agrees with the earlier findings in 27 matched pairs of tumors and normal cells and tissue." (PMID 41244835, 2025). "Further analysis of oncogenes and tumor suppressor genes revealed that tumors exhibited elevated expression of oncogenes such as ZWINT and ZIC4, and decreased expression of tumor suppressors like HAMP and CXCL14." (PMID 41388520, 2025). "According to the HAMP expression levels, we divided the samples into the tumor and normal expression groups and analyzed the differences in 22 immune cells." (PMID 36673667, 2023). "Nevertheless, our experiment is the first to investigate the effect of a high expression level of HAMP in KIRC on the prognosis of tumor patients, and it provides a possible target for clinical treatment." (PMID 36673667, 2023). "Our study revealed higher HAMP expression levels in tumor tissues including KIRC, which were related to poor prognosis in terms of OS, DSS and PFI." (PMID 36673667, 2023). "When examining the relevance of the tumor stage, we noticed that the expression of HAMP displayed a striking decrease in the early stage of HCC." (PMID 36830729, 2023). "In our study, HAMP was highly expressed in tumor tissue, and we used CRC cells and tissue to validate its high expression in tumors." (PMID 35992796, 2022). "Taken together, HAMP is promising as a novel biomarkers for predicting tumor progression and guiding the suitable treatment for ccRCC patients." (PMID 36585741, 2022). "A further mechanistic investigation is underway by our group to elucidate the functional role of IL34 in HAMP expression and tumor progression." (PMID 36532749, 2022). "In patients with a higher tumor mutation burden (TMB), HAMP upregulation showed a substantial impact on overall survival than those with a lower TMB (HR 5.29 vs. 3.75)." (PMID 36532749, 2022). "Phenotype association analysis suggested all of hub genes involved in tumor development, and it seems CRYBB1, CEACAM4, and HAMP correlated with ccRCC progression more than another two (RIMBP3C and LYL1)." (PMID 34402193, 2021). "Spearman correlations analysis showed that CRYBB1, CEACAM4, HAMP, and LYL1 were highly positively associated with tumor‐infiltrating lymphocytes in ccRCC." (PMID 34402193, 2021). "The expression of HAMP was assessed in 423 samples, including 373 tumor tissue samples and 50 adjacent tissue samples from TCGA dataset." (PMID 31052210, 2019). "In summary, our study showed that the expression of HAMP was downregulated in tumor tissues compared with adjacent tumor tissues in HCC patients." (PMID 31052210, 2019). "Analysis of HAMP expression of HCC tissues with M0 or M1 cancer metastasis grade showed that tumor tissues with higher metastasis grade had lower HAMP expression." (PMID 31052210, 2019). "The relationship between the expression of HAMP and prognosis and tumor was then investigated." (PMID 41244835, 2025).
tumor (continued). "Moreover, since the mRNA and protein expression levels of HAMP varied between normal and tumor tissues in KIRC, it showed high prognostic potential." (PMID 36673667, 2023). "Similarly, HAMP expression levels were also higher in tumor tissues than in paired para-carcinoma tissues." (PMID 36585741, 2022). "As HAMP/hepcidin could regulate the activation of this pathway, the authors proposed HAMP as a tumour suppressor gene." (PMID 35264787, 2022). "Hepcidin (HAMP) plays a key role in tumor cell proliferation and metastasis." (PMID 35646056, 2022). "After we had analyzed the somatic copy number alterations (SCNAs) in KIRC, there were significant differences in B cells, CD8+ T cells, CD4+ cells, neutrophils and dendritic cells, which confirmed the prediction that HAMP may regulate the tumor process through immune infiltration." (PMID 36673667, 2023). "Moreover, the relationship between the expression level of HAMP and various immune cells’ gene markers indicates that HAMP could regulate the tumor immune microenvironment." (PMID 36673667, 2023). "We further accessed RNA-seq data from tumor tissues of 371 patients and 50 adjacent NTL available at The Cancer Genome Atlas (TCGA) database and inspected for changes in TFR1 and HAMP mRNA levels." (PMID 39820815, 2025). "The results showed that the expression of HAMP, FDFT1, GDF15, TFAP2C all increased in tumor tissues, indicating their meaningful regulatory roles in CRC." (PMID 34249766, 2021). "The results showed that KIAA1429, HAMP, AQP9, CCL13, and CCL21 were significantly negatively correlated with tumor purity, and KIAA1429 was highly correlated with B cells, CD8 T cells, CD4 T cells, macrophages, neutrophils, and dendritic cells." (PMID 34422053, 2021). "Tumor microenvironment analysis in TISIDB and GSE73731 confirmed that CRYBB1, CEACAM4, HAMP, and LYL1 were highly related to tumor‐infiltrating lymphocytes." (PMID 34402193, 2021). "Spearman correlations analysis indicated that CRYBB1, CEACAM4, HAMP, and LYL1 were positively related to different kinds of tumor‐infiltrating lymphocytes across many tumor types while RIMBP3C showed consistently statistical insignificance." (PMID 34402193, 2021).
infection (19 papers, 2012 to 2025). The state of being infected such as from the introduction of a foreign agent such as serum, vaccine, antigenic substance or organism. "The critical role of HAMP in the host response to Salmonella infection was validated by showing increased susceptibility to infection in Hamp-deficient mice and significant survival benefits in Ank1+/Ity16 heterozygous mice treated with HAMP peptide." (PMID 23390527, 2013). "Conversely, during inflammation and infection, the expression of hepcidin antimicrobial peptide (HAMP) is increased because self-defense mechanisms result in a decrease in circulating iron due to the sequestration of iron by macrophages." (PMID 41244835, 2025). "In our experiments, only cells infected with E. coli showed strong induction in HAMP mRNA, already after 3h of intracellular infection." (PMID 35663465, 2022). "Surprisingly, we also noted that HAMP and LCN2 genes, encoding hepcidin and lipocalin, respectively, two of the main players of hypoferremia in response to infection by other pathogens, remained unaffected after infection." (PMID 34035436, 2021). "HAMP expression was higher during infection with WT V. vulnificus than during infection with ΔrtxA1V. vulnificus." (PMID 32817457, 2020). "In spleen, kidney and intestine, the expression level of HAMP gene significant increased from 12 h to 24 h (P<0.05), the high expression level were checked at 24 h after infection, following by a recovery to normal level after 72 h except for kidney." (PMID 22511989, 2012). "In liver, the expression level of HAMP gene sustained decreased from infection starting time to 72 h after challenge; the lowest expression level was checked at 36 h." (PMID 22511989, 2012). "This was shown by a strong increase in HAMP mRNA levels after infection of the cells." (PMID 35181867, 2022). "Based on these observations we postulated that vitamin D (25D)-deficiency associated with CKD may predispose to infection through impaired regulation of CAMP and HAMP activity." (PMID 25549329, 2014). "Expression levels of HAMP gene were found first up-regulated and then down-regulated, and finally recovery to normal level throughout the infection process suggest that crucial interference of cellular function occurs under a semilethal concentration of pathogenic bacteria in immune tissues." (PMID 22511989, 2012). "Interestingly, the expression level of HAMP gene sustained decreased from infection starting time to 72 h after challenge in the miiuy croaker liver." (PMID 22511989, 2012). "However, at 24 h post-infection, the expression of HAMP showed down-regulation." (PMID 32275661, 2020). "However, HAMP was significantly down-regulated at 2 h post-infection with A. salmonicida." (PMID 31231379, 2019). "After the infection, in the Fe-Gly addition group, the expression of hepatic FTL gene was significantly decreased (p < 0.05), the expression of HAMP gene tended to decrease (p = 0.050), and the expression of FTH gene had a tendency to decrease (p = 0.051)." (PMID 39944187, 2025). "Infection with norovirus also increases CRP, AGP, and HAMP, and promotes changes in levels of micronutrients iron and vitamin A." (PMID 36675141, 2023). "At 8 weeks post-infection, expression of BMP6, HAMP, FPN1, FTH1, NRF2, and LCN2 was significantly up-regulated, while HFE1 was significantly down-regulated by Fe-supplementation, compared to the placebo group." (PMID 31382404, 2019). "Fe-supplementation resulted in a significant down-regulation of HFE3 (TFR2), HAMP, FPN1, and LCN2 while BMP6 and FTH1 were significantly up-regulated, compared to the placebo group, at 4 weeks post-infection." (PMID 31382404, 2019). "In response to infection, an antibacterial peptide hormone, HEPCIDIN ANTIMICROBIAL PEPTIDE (HAMP), is produced." (PMID 30150923, 2018).
infection (continued). "Indeed, HAMP expression increases in alveolar macrophages during inflammation and degradation of FPN decreases iron efflux, meaning that hepcidin protects the lungs against infection or inflammation by creating an iron-limited environment and decreased iron-mediated oxidative lung injury." (PMID 41007630, 2025).
cancer (15 papers, 2008 to 2025). A tumor composed of atypical neoplastic, often pleomorphic cells that invade other tissues. "Based on the GO and KEGG pathway analyses, we found that HAMP was significantly associated with several immune response pathways and cancer pathways." (PMID 36673667, 2023). "An increasing number of studies have revealed that abnormal expression or activation of HAMP is a common phenomenon in multiple malignancies, and it has been demonstrated that HAMP expression is significantly associated with cancers, including." (PMID 36585741, 2022). "In addition, CEACAM4 was enriched in VEGF signaling pathway (p‐value: 0.027) and MAPK signaling pathway (p‐value: 0.040) and HAMP was significantly associated with pathways in cancer (p‐value: 3.24e−04) and MAPK signaling pathway (p‐value: 6.98e−03)." (PMID 34402193, 2021). "To confirm this inference, we used publicly available cancer databases and R programming to assess the expression of HAMP in KIRC and its prognostic and predictive role." (PMID 36673667, 2023). "We first analyzed the mRNA expression levels of HAMP in different cancers with Oncomine and R programming based on the TCGA database." (PMID 36673667, 2023). "Since epigenetic alterations have been proven to play a role in cancer biology, we also explored the promoter methylation level of HAMP in KIRC and normal samples with UALCAN." (PMID 36673667, 2023). "HAMP was expressed in seven of the eight proliferative hepatocytes from para-carcinoma tissue and three of the 545 proliferative hepatocytes from HCC tissue samples." (PMID 34001107, 2021). "In addition, HAMP upregulation was also evidenced in other human cancer types derived from the breast, colon, lung, head-neck, stomach, and esophagus." (PMID 36532749, 2022). "Specific HAMP expression in hepatocytes from para-carcinoma tissue was confirmed." (PMID 34001107, 2021). "Moreover, for FCER1G, LGALS9, TWEM149, EVI2B, and HAMP, the gene expression levels in the cancer population were higher than those in the normal population." (PMID 32903590, 2020). "Thus, data showed that reduced HAMP expression could activate this pathway, and thereby promote cancer cell proliferation and migration/metastasis, eventually aggravating HCC pathogenesis." (PMID 35264787, 2022). "In view of the important role of HAMP in cancer, it may serve as a potential biomarker for ccRCC." (PMID 36585741, 2022). "Next, we found that the expression level of HAMP in RCC tissue was substantially and significantly higher than that in para-carcinoma tissues." (PMID 36585741, 2022). "We discovered that HAMP was specifically expressed in hepatocytes and SLC40A1 was specifically expressed in macrophages in HCC and para-carcinoma tissues." (PMID 34001107, 2021). "We employed two large-scale bulk HCC RNA-Seq/microarray datasets to compare the expression of HAMP, CD5L, CETP, MARCO, and CFP between HCC and para-carcinoma tissue samples." (PMID 34001107, 2021). "It is well known that HAMP plays an essential negative role in iron homeostasis, and its production of hepcidin was proven to be expressed in many cancers and non-cancer tissues." (PMID 36673667, 2023). "Given that HAMP may be a potential biomarker for KIRC, we first used the Oncomine database to analyze the mRNA expression levels of HAMP in multiple types of cancer and normal tissues." (PMID 36673667, 2023). "In this study, our data revealed that HAMP upregulation-dependent negative impact on overall survival was diminished in an anti-cancer immune cell-enriched environment." (PMID 36532749, 2022). "We further investigated HAMP expression in all hepatocytes from HCC and para-carcinoma tissues." (PMID 34001107, 2021).